CXCL8 (C-X-C motif chemokine ligand 8)
Diseases named in the same sentence as CXCL8 in open-access papers (continued):
Sharing a sentence is not in itself a finding about the gene and the disease.
psoriasis (279 papers, 2006 to 2026). An autoimmune condition characterized by red, well-delineated plaques with silvery scales that are usually on the extensor surfaces and scalp. "The hallmark type-3 inflammation seen in psoriasis is largely driven by Th17 and Tc17 cells’ interactions with keratinocytes, driving the robust secretion of chemokines like CXCL8, leading to characteristic neutrophilic infiltrates in psoriatic lesions." (PMID 41479908, 2025). "CXCL8 and CXCL13 have already been implicated in early disease stages, with CXCL8 upregulated in mild psoriasis and CXCL13 expressed by lesion-infiltrating T cells, correlating with IL-17A levels." (PMID 40943056, 2025). "CXCL8 has been shown to be linked to several inflammatory states including psoriasis and being involved in wound healing." (PMID 34086734, 2021). "Our research revealed that elevated levels of CXCL1, CXCL2, and CXCL8 in psoriasis patients are significantly associated with the infiltration of immune cells such as T cells, neutrophils, and DCs, hence providing considerable diagnostic value with an AUC of 0.989, 0.963, and 0.982, respectively." (PMID 38829444, 2024). "According to the previous report, abnormal signal transduction in CXCL8-CXCR/2 axis may cause inflammatory diseases including psoriasis and inflammatory bowel diseases which suggests CXCL8 maybe a potential therapeutic target for psoriasis." (PMID 35586812, 2022). "In our study, we found that fast responders with psoriasis was mainly involved in low-density neutrophils, speculated that this may be caused by CXCL8 reduction." (PMID 35693833, 2022). "To confirm the results obtained by RNA‐seq, we performed qPCR to detect and quantify CXCL1, CXCL2, CXCL8, CSFR3, OSM and TREM1, in addition to the psoriasis‐associated genes IL‐17A and IL‐23." (PMID 40181552, 2025). "CXCL8 plays a crucial role in psoriasis pathogenesis, particularly in neutrophil infiltration, angiogenesis and keratinocyte proliferation within psoriatic lesions." (PMID 40540498, 2025). "Chemokines encoded by CCR7, CCL2, CCL19, CXCL8, CXCL1, and CXCL2 genes have been identified as potential biomarkers of psoriasis." (PMID 40906403, 2025). "MSC exosomes also suppressed DC maturation and activation and inhibited the release of pro-inflammatory cytokines (TNF-α, IFN-γ, IL-1β), chemokines (CCL20 and CXCL8), and psoriasis-specific cytokines (IL-23)." (PMID 41007656, 2025). "Although miR-210 upregulation in psoriasis has previously been noted, the link between miR-210 and CXCL8 was first discovered in our research." (PMID 38829444, 2024). "Our findings confirm that the skin surface hBD-2, IL-1α, CXCL-1/2, and CXCL-8 are markers for the psoriasis severity." (PMID 38003437, 2023). "It is well known that keratinocytes attract neutrophils by releasing CXCL-1 and CXCL-8 expression in the context of psoriasis." (PMID 35401573, 2022). "We constructed the predicted PPI networks and functional modules related to psoriasis and atopic dermatitis and distinguished the key candidate target genes CXCL8, STAT1, and MMP9 in the diagnosis and therapy of similar pathogenesis." (PMID 35586812, 2022). "We discovered THY1+, THY1−ACTA2high, and CXCL8+ pericytes in AD and psoriasis, mirroring those in DD." (PMID 35320046, 2022). "IL-8 (CXCL8) participates in the pathophysiology of psoriasis recruiting neutrophils and other inflammatory leukocytes." (PMID 34697538, 2021). "Platelets, which are often elevated during infectious and inflammatory diseases, store a number of inflammatory cytokines and chemokines that play crucial roles in psoriasis, such as IL-1β and CXCL8." (PMID 34565327, 2021). "The Th17 chemokine CXCL8 was secreted to a higher amount by psoriasis-derived T cells (3.5 versus 2.3 ng/ml, p = 0.72), while the Th2-associated chemokine CCL-5 was released more by ACD T cells (4.5 versus 0.9 ng/ml, p = 0.53)." (PMID 25058585, 2014).
psoriasis (continued). "The Degree algorithm in CytoScape software was then used to rank the importance of these common genes, and the results showed that genes such as PTGS2 (COX-2) and CXCL8 played the role of core target genes in the process of ergothioneine in alleviating psoriasis." (PMID 40046751, 2025). "Additionally, miR-155 was found to indirectly affect CXCL8 production, thereby influencing psoriasis progression, which supports our findings." (PMID 38829444, 2024). "Similarly, the presence of the IL-8 receptor was increased in psoriatic patients, and recent bioinformatic analysis indicated CXCL-8 (IL-8)-related genes were a novel gene hub, related to 22 subtypes of immune cells essential in psoriasis." (PMID 38672088, 2024). "Our findings indicate increased CXCL8 expression, suggesting that elevated miR-203 levels might positively influence psoriasis by moderating CXCL8’s abnormal expression, or it might represent a compensatory response to the abnormal expression of CXCL8." (PMID 38829444, 2024). "Additionally, we explored the skin lesions of psoriasis patients and found significantly higher expression of CXCL8, IL-1B, S100A9, and S100A12 in the affected skin areas compared to unaffected regions." (PMID 39014096, 2024). "CXCL8 levels in the serum of patients in psoriasis were reported by Zhen." (PMID 35693833, 2022). "The effects of IL‐38 on psoriasis development were demonstrated through IL‐38 injection into imiquimod‐induced psoriatic mice, showed down‐regulated levels of loricrin, CXCL8, CXCL20 and IL‐6, and ameliorated the manifestations, such as reduction of acanthosis and dermal inflammatory infiltrate." (PMID 33079487, 2020). "In addition, NF-κB activity is regulated by CARD14, a protein of “signalosome” complex involved in activation of innate immunity molecules (i.e., IL-36γ, CXCL8, and CCL20), whose gene shows different allelic variants associated to psoriasis." (PMID 30034395, 2018). "However, the only successful anti-chemokine antibody developed thus far is a topical anti-CXCL8 monoclonal antibody for psoriasis (Abcream, a product of Anogen), which was approved in China." (PMID 28792472, 2017). "Induction of CXCL8 and TNF-α by resistin in monocytes population in blood is also linked with psoriasis pathophysiology and TNF-α stimulates keratinocyte proliferation and T cells recruitment to the skin, thus a close relationship between resistin and TNF-α-mediated inflammation exists in psoriasis." (PMID 25980409, 2015). "This hypothesis is supported by previous studies; for example, the S100A8/A9 complex is significantly elevated in psoriasis serum and positively correlates with disease activity, while CXCL8 inhibitors can significantly reduce intestinal inflammation in animal models." (PMID 40540498, 2025). "Therefore, treatment methods for psoriasis targeted at modulating CXCL8 expression such as demonstrated by mono-RL and di-RL in this study could be an important step towards psoriasis treatments." (PMID 36441210, 2023). "IL36G was also highly expressed in psoriasis, and correlation analysis indicated that IL36G was closely related to IL36A, IL19, CXCL1, and CXCL8, all of which participate in the pathogenesis of psoriasis." (PMID 40159643, 2025). "The differential expression analysis identified several upregulated differentially expressed genes, including OSM, CXCL8, TREM1, CXCL1, CSF3R, BCL2A1 and CXCL2, in relapsed psoriasis skin compared with baseline lesional skin." (PMID 40181552, 2025). "In conclusion, our study highlights six chemokine genes (CCR7, CCL2, CCL19, CXCL8, CXCL1, and CXCL2) as potential biomarkers in psoriasis, providing insights into the immune and inflammatory responses as pivotal instances in disease pathogenesis." (PMID 38829444, 2024). "TNF‐α, IL‐1β, IL‐23, IL‐17, IL‐22, Cox2, and iNOS are all inflammatory cytokines involved in the pathogenesis of psoriasis, and CXCL1, CXCL8, and CCL20 are antimicrobial peptides and chemokines produced by keratinocytes." (PMID 38967379, 2024).
psoriasis (continued). "The study highlights six chemokine genes (CCR7, CCL2, CCL19, CXCL8, CXCL1, and CXCL2) as potential biomarkers in psoriasis, which are significantly involved in immune and inflammatory responses." (PMID 38829444, 2024). "To identify potential therapeutic options for psoriasis and AMI, we screened drugs targeting CXCL8, IL1B, S100A9, and S100A12 using the DsigDB database." (PMID 39014096, 2024). "Our study highlighted CCR7, CCL2, CCL19, CXCL8, CXCL1, and CXCL2 as potential inflammatory biomarkers in psoriasis, illuminating their molecular mechanisms." (PMID 38829444, 2024). "To further investigate the role of SLPI, S100A9, IL1B, CYBB, CXCL8, S100A12, and CXCL1 genes in the immune microenvironment of psoriasis, we examined inflammatory cell infiltration." (PMID 39014096, 2024). "However, the dominant immune response in psoriasis is T helper 17 (Th17), whose characteristic cytokines are interleukin 17A (IL-17A), interleukin 17F (IL-17F), interleukin 21 (IL-21), interleukin 22 (IL-22), interleukin 29 (IL-29), interleukin 8 (CXCL-8), and tumor necrosis factor α (TNF-α)." (PMID 38001807, 2023). "Leptin increases the synthesis of pro-inflammatory mediators that play an important role in the development of psoriasis, such as TNF-α and CXCL8." (PMID 36675592, 2023). "Leptin has been shown to increase the synthesis of pro-inflammatory mediators involved in the pathogenesis of psoriasis, such as IL-1, IL-6, TNF-α, and CXCL8." (PMID 36675592, 2023). "It induces the expression of other psoriasis signature genes, such as IL36G, S100A15, DEFB4A, S100A9, CXCL8, TNIP3 (coding TNF-α-induced-protein 3 or TNFAIP3), and LCN2 (by synergy of IL-17C with TNF-α) in keratinocytes." (PMID 36928592, 2023). "Neutrophil infiltration and tortuous telangiectasia are pathological features of psoriasis, and MMP-9 can decompose a 62-amino acid peptide from IL-8 (CXCL8/CL8) to increase the chemotactic activity of neutrophils." (PMID 36950008, 2023). "The levels of chemokines such as CXCL8 and CCL20 were dramatically increased in the TNF-α/IL-17/IFN-γ-induced HaCaT psoriasis model." (PMID 36015080, 2022). "As well as in psoriasis, the enrichment of IL-17A-producing immune cells leads to produce high levels of IL-17A, which further stimulates keratinocytes producing CCL20, CXCL8, and IL-36γ to recruit more IL-17A-producing immune cells and neutrophils." (PMID 35069008, 2022). "A total of 389 significant genes were common to both hepatitis C and psoriasis, which mainly involved IL6, TNF, IL10, ALB, STAT3 and CXCL8." (PMID 34215260, 2021). "Most of these targets exhibited abnormal expression and were designated as the therapeutic targets in psoriasis, such as the cytokines and chemokines (IL-1β, IL-6, TNF, IFN-γ, CXCL8, CCL2)." (PMID 34168554, 2021). "CXCL8 and CXCL10 expressions have been reported to increase in the lesional skin from patients with psoriasis." (PMID 33149756, 2020). "CXCL8 is regulated by other cytokines such as IL17A and IL1B, which is critical for the pathogenesis of psoriasis and influences lesional keratinocytes of psoriasis." (PMID 32785106, 2020). "IL-17A affects, in particular, keratinocyte immune function, by inducing the release of antimicrobial peptides and chemokines, such as CXCL8/IL-8 and CXCL1/GRO-α, responsible for the accumulation of neutrophils in the early phase of psoriasis inflammation." (PMID 32352958, 2020). "In accordance with the accumulation of neutrophils in psoriasis, the gene expression of neutrophilic cytochemokines CXCL1, CXCL2, CXCL8, and IL-36 is upregulated in the lesional skin of psoriasis." (PMID 32070069, 2020). "IL17 in psoriasis has the ability to recruit neutrophils and macrophages by inducing keratinocytes to produce CXCL1, CXCL2, CXCL3, CXCL5, and CXCL8 (i.e., IL8)." (PMID 33050592, 2020).
psoriasis (continued). "It has been proposed, that the primary cellular effect of IL-36 cytokines in psoriasis is their impact on neutrophil inflammation through activation of neutrophil chemokines CXCL1 and CXCL8." (PMID 30634937, 2019). "IL-17A not only contributes to the epidermal abnormalities typical of psoriasis, but also induces the expression of chemokines in keratinocytes such as GRO-α (CXCL1) and IL-8 (CXCL8), which orchestrate the recruitment of neutrophils to psoriatic lesions." (PMID 25828362, 2015). "Similarly, in psoriasis, TOPK regulates neutrophil chemokines such as CXCL1, CXCL2, and CXCL8 by activating STAT3 and NF-κB p65 in keratinocytes, thereby promoting neutrophil infiltration and psoriasis progression." (PMID 41362722, 2026). "Bimekizumab treatment completely reversed the levels of cytokines/chemokines, anti‐microbial peptides, or proliferation‐related molecules, such as CXCL8, CCL20, IL‐17A, IL‐17F, IL‐17C, keratin 16, IL‐36γ, DEFB4, or S100A7, in psoriasis lesional skin to the levels of non‐lesional skin." (PMID 38482898, 2024). "Interestingly, a closer inspection of single-cell profiles identified some differences between prurigo nodularis and psoriasis lesions, with WNT5A+/IL24+ fibroblasts expressing TBX3 and CXCL8 only in the latter." (PMID 38291032, 2024). "We brought forth the conclusion that CXCL8, STAT1, and MMP9 may essentially implicate in disease of psoriasis and atopic dermatitis as the potential therapeutic targets." (PMID 35586812, 2022). "In addition, secoligulene downregulated the expression of chemokines such as CXCL8 and CCL20 in the TNF-α/IL-17/IFN-γ induced HaCaT psoriasis model." (PMID 36015080, 2022). "In addition, CXCL8, STAT1, and MMP9 were upregulated in both psoriasis and atopic dermatitis disease model samples vs. normal samples by the Western blot analyses." (PMID 35586812, 2022). "In addition, IL-24 overexpression in psoriasis prompts the expression of pro-inflammatory chemokines CXCL1, CXCL8, and CCL20." (PMID 34638757, 2021). "Scratch injury upregulates the gene expression of CCL20, CXCL8, and IL36G, which may be related to the scratch-induced Koebner phenomenon frequently observed in patients with psoriasis." (PMID 32070069, 2020). "The expression of Th1 and Th17 recruiting chemokines CXCL1, CXCL8 and CCL20 is upregulated in psoriasis skin but the precise contribution of DCs to chemokine secretion in psoriasis is unknown." (PMID 25301671, 2015). "ABX-IL8, a fully humanized monoclonal anti-CXCL8 antibody produced by Abgenix using XenoMouse technology has been assessed in clinical trials for rheumatoid arthritis, psoriasis and chronic obstructive pulmonary disease (COPD)." (PMID 24276377, 2013). "Moreover, this study found significant upregulation of well-known psoriasis-related genes such as β-defensin 2, CD68, and cytokines IL-8 (CXCL8), SCYA2 (MCP-1/CCL2), and platelet-derived endothelial cell growth factor 1 in psoriatic skin lesions." (PMID 19884985, 2009). "And studies have shown that CXCL8 could recruit neutrophils and CCL20 chemotactically attracts IL-17A-producing immune cells, further creating an IL-17A-rich environment and accelerating the pathological progression of psoriasis." (PMID 38803495, 2024). "In patients with psoriasis, neutrophils are pre-activated and form a NET in psoriatic skin lesions NET promote keratinocyte to secrete high levels of proinflammatory factors (LCN2, IL-36γ, CXCL8, and CXCL1) by activating TLR4/IL-36R crossers and the downstream MyD88/NF-κB signaling pathway." (PMID 39737188, 2024). "In the pathogenesis of psoriasis, IL-17 interacts with keratinocytes to promote the production of antimicrobial peptides, proinflammatory cytokines and chemokines (IL-1β, TNF-α, IL-6, IL-17C, CXCL1, CXCL3, CXCL5, CXCL8 [IL-8] and CCL20) and proliferative cytokines (IL-19)." (PMID 35514987, 2022).
psoriasis (continued). "Furthermore, LL37 induces CXCL8 and CXCL1 chemokines through IL-36R signaling in psoriatic keratinocytes, which would, in turn, determine the recruitment and the burst of neutrophils in lesional skin, typical of the early phase of psoriasis." (PMID 30034395, 2018). "For example, chemokines like MIG/CXCL9, IL-10/CXCL10, IL-8/CXCL8, MCP-1/CCL2 and MIP-3α/CCL20 released from epidermal keratinocytes function as potent chemoattractants for monocytes, neutrophils, Langerhans cells, DCs and T cells, which are key cells in psoriasis." (PMID 29232931, 2017). "Downregulation of ULK1 with siRNA did not affect the expression of most psoriasis-related cytokines in PHK without stimulation but increased the transcripts of TNF and CXCL8 in the presence of IL-17A." (PMID 34421918, 2021).